CCNF (cyclin F)
Diseases named in the same sentence as CCNF in open-access papers (continued):
Sharing a sentence is not in itself a finding about the gene and the disease.
tumor (continued). "CCNF expression values were compared between tumor tissues and adjacent tissues, and the results showed that the expression of CCNF was significantly increased in tumor tissues compared to that in adjacent tissues." (PMID 34397798, 2021). "We used TCGA data and Gene Expression Omnibus (GEO) data to analyze the differential expression of CCNF between tumor and adjacent tissues and the relationship between CCNF and clinical characteristics." (PMID 34397798, 2021). "Specifically, multivariate Cox analysis revealed that CCNF mRNA expression was an independent predictor of worse OS after adjustment for histologic grade, tumor status, nodal status, age, and gender (HR = 1.66, 95% CI 1.04–2.67; p = 0.03)." (PMID 33670609, 2021). "CCNF expression, tumor size, and clinical stage were shown to be responsible for the poor outcome of HCC patients in the univariate Cox analysis." (PMID 34397798, 2021). "FBXO1, also known as cyclin F, meditates centrosome duplication and is critical for maintaining genome integrity, thus it has been regarded as an emerging tumor suppresser." (PMID 30341246, 2019). "CDC20, AURKA, and CCNF are highly expressed in a variety of tumor cell lines." (PMID 39895786, 2025). "However, the abundance and gene markers of different tumor-infiltrating immune cells were found to be only weakly to moderately correlated with CCNF (the range for correlation coefficients: 0.1–0.47)." (PMID 38654021, 2024). "Moreover, GEPIA2 was applied to explore the correlation between CCNF expression and gene markers of tumor-infiltrating immune cells in TCGA-KIRC." (PMID 38654021, 2024). "Notably, when analyzed as a continuous variable using the UALCAN web tool, CCNF expression increased with increasing tumor grade." (PMID 38654021, 2024). "Statistically significant univariable hazard ratios (HRs) were found for cyclin F (HR 1.91, 95% CI 1.23–2.98), age at diagnosis (HR 1.63, 95% CI 1.09–2.46), sex (HR 0.57, 95% CI 0.37–0.88), tumor grade (HR 3.46, 95% CI 1.90–6.31), and nodal status (HR 3.44, 95% CI 1.55–7.64)." (PMID 38654021, 2024). "Likewise, CCNF expression was higher in tumor tissues than in matched adjacent normal tissues or non-paired normal tissue but not in metastasis from the gene chip data of the TNMplot." (PMID 38654021, 2024). "Furthermore, in TMA and TCGA cohorts, patients with more aggressive tumor features more frequently had cyclin F/CCNF-high than cyclin F/CCNF-low expression." (PMID 38654021, 2024). "The findings revealed elevated CCNF expression in 11 tumor tissues compared to normal tissues." (PMID 37670965, 2023). "These two reports suggest that CCNF is likely to be a tumor suppressor gene." (PMID 37168372, 2023). "Moreover, through immune infiltration and enrichment analyses, we uncovered the contribution of elevated CCNF expression to the tumor immunosuppressive microenvironment." (PMID 37670965, 2023). "The results unveiled distinct expression patterns of CCNF between tumor and normal tissues." (PMID 37670965, 2023). "Furthermore, we examined the expression of CCNF protein levels by analyzing the immunohistochemistry (IHC) results of both normal and tumor tissues." (PMID 37670965, 2023). "CCNF catalyzes the transfer of ubiquitin molecules from E2 ubiquitin-conjugating enzymes to target proteins, thereby regulating the G1/S or G2/M transition of tumor cells." (PMID 37168372, 2023). "Given the characteristics of the substrates of SCF-cyclin F, the latter might be expected to act as a tumor suppressor, and most experimental studies have recently supported this thesis; however, those supporting its pro-tumorigenic activity also exist." (PMID 33670609, 2021). "Given the characteristics of the substrates of SCFCyclin F, cyclin F might be expected to serve as a tumor suppressor." (PMID 32429232, 2020). "Moreover, the expression of CCNF increases proportionally with tumor grade." (PMID 38654021, 2024).
tumor (continued). "Thus, it would be clinically relevant to investigate whether the USP7-cyclin F axis contributes to tumor progression and aggressiveness in these specific contexts." (PMID 36342772, 2022). "Therefore, in the future, it would be interesting to design anti-BRCA strategies by counterbalancing the activities of E2 and E3 ligases, for example, to maintain CCNF to suppress tumor-promoter RRM2 and/or inhibit FBXL8 and FZR1 to reduce their targeting of tumor-suppressor CCNF protein." (PMID 34201347, 2021). "In conclusion, CCNF expression level significantly influences the TIME and provides valuable insights for the development of tumor immunotherapy strategies." (PMID 37670965, 2023). "Given that cyclin F, RRM2, and SPDL1 are considered GIN-related proteins, we also analyzed their expression in relationship to tumor aneuploidy score and fraction genome altered (TCGA cohort) or MSH6 protein level (our cohort)." (PMID 33670609, 2021). "Meanwhile, the expression of CCNA2 and CCNB1 was positively correlated with tumor-killing immune cells, such as CD8+ T cells.The copy numbers of CCNA2, CCNB1, CCND1, CCNE1, and CCNF was positively related to gene expression." (PMID 33996604, 2021). "We found cyclin F, RRM2, and SPDL1 to be overexpressed at both protein and mRNA levels in tumor tissues compared to respective controls." (PMID 33670609, 2021). "We first determined the IHC expression of cyclin F in two independent TMA cohorts: in-house cohort (TMA_1), consisting of 108 ccRCC tissues and 37 adjacent non-tumor tissues, and the other, commercially purchased one (TMA_2), encompassing 192 ccRCC cases and 16 samples of normal renal tissue." (PMID 38654021, 2024). "Faint cytoplasmic staining of cyclin F was occasionally observed in a renal tubular epithelium of adjacent non-tumor tissues but not in a renal tubular epithelium of normal tissues." (PMID 38654021, 2024). "Two custom dPCR probes were designed to target two somatic mutations, one in the CEP135 gene (CEP135:c.3389C>T:p.S1130F) and the other in the CCNF gene (CCNF:c.541-31G>C), identified through whole-exome sequencing of the tumor and absent in genomic DNA." (PMID 39596073, 2024). "We conducted an investigation into the clinical correlation of CCNF expression based on TNM staging (T: tumor size, N: lymph node involvement, M: distant metastasis)." (PMID 37670965, 2023). "In this study, the differential expression analysis showed that among all cyclin family members, there were six significant DEGs (CCNA2, CCNB1, CCND1, CCNE1, CCNF, and CCNJL), five of which were overexpressed in tumor samples compared to normal controls, while CCNJL was downregulated." (PMID 33996604, 2021). "Cyclin F expression was obviously increased in PDAC tissues compared with non-malignant tissues adjacent to the tumor area (p < 0.0001)." (PMID 33670609, 2021). "Our findings suggest that cyclin F/CCNF expression is likely to have an essential role in ccRCC pathobiology through regulating multiple oncogenic signaling pathways and affecting the tumor immune microenvironment and may serve as prognostic biomarker and promising therapeutic target in ccRCC." (PMID 38654021, 2024). "In addition, CCNF expression demonstrated a significant negative correlation with tumor purity in KIRC (r = − 0.122, p = 0.00853; data not shown)." (PMID 38654021, 2024). "Furthermore, cyclin F immunoreactivity was observed in most ccRCCs, in a minority of tumor-adjacent normal tissues, and neither of normal renal tissues." (PMID 38654021, 2024). "Although the correlation values were not statistically significant, CCNF was visibly related to all infiltrating immune cells, suggesting it may play a modest role in tumor growth and the maintenance of immune suppression." (PMID 34397798, 2021).
neurodegenerative disease (5 papers, 2016 to 2023). A disorder of the central nervous system characterized by gradual and progressive loss of neural tissue and neurologic function. "Importantly, we found that mutant cyclin F p.S621G abnormally ubiquitylates p62, and leads to decreased p62 foci formation and aberrant solubility, which are events that have been linked to neurodegenerative diseases including ALS and FTD." (PMID 37243816, 2023). "UPS impairment underlies many neurodegenerative diseases, including ALS, and overexpression of a number of ALS-associated proteins (including CCNF), can cause UPS dysfunction." (PMID 37220877, 2023). "There is also evidence that defects in molecules functionally related to cyclin F play a role in other neurodegenerative diseases." (PMID 27080313, 2016). "The roles of cyclin F, which acts as a cyclin as well as an F-box protein, have not been explored in this context, and thus can be further investigated to understand their relevance in mediating neurodegenerative diseases." (PMID 31884567, 2020).
neurological diseases (2 papers, 2021 to 2023). "Besides, several genes appear to be associated with other neurological disorders, such as CCNF and ANXA11 linked to FTD." (PMID 37250416, 2023).
infection (1 paper, 2017). The state of being infected such as from the introduction of a foreign agent such as serum, vaccine, antigenic substance or organism. "Complete restoration of Vif expression was observed with the addition of MG132 in the cyclin F overexpressed condition, demonstrating that cyclin F mediates proteasomal degradation of Vif during infection." (PMID 28184007, 2017). "Further investigation of the role of cyclin F in infection revealed its negative regulatory influence on HIV-1 viral infectivity." (PMID 28184007, 2017). "Vif is a late expressing viral protein, and cyclin F exhibited progressive down-regulation with infection." (PMID 28184007, 2017). "Cytoplasmic and nuclear extracts were prepared and analyzed, and they showed the presence of cyclin F and Vif in both the cytoplasm as well as the nucleus during infection." (PMID 28184007, 2017). "Immunoblot analyses of the lysates were performed, which demonstrated that during infection, when cyclin F expression is significantly down-regulated, Vif expression is elevated ultimately leading to an attenuation of A3G expression." (PMID 28184007, 2017). "Analysis of the endogenous interaction of cyclin F and Vif in infected T cells demonstrated that although cyclin F is down-regulated during infection, the residual endogenous cyclin F can still interact with Vif under physiological conditions." (PMID 28184007, 2017). "Cyclin F was identified from the gene expression analysis as a significantly down-regulated gene during infection." (PMID 28184007, 2017). "Cyclin F, as expected, showed a progressive down-regulation, whereas Vif, a late expressing viral protein, increased and stabilized its expression with the progression of infection." (PMID 28184007, 2017). "The biological interaction of cyclin F and Vif followed by identification of cyclin F as a negative regulator of Vif and thereby viral infectivity raises the possibility that cyclin F down-regulation during infection in CD4+ T cells could be a virus-mediated effect." (PMID 28184007, 2017). "As cyclin F undergoes down-regulation during infection, to understand its role in HIV-1 pathogenesis, we overexpressed cyclin F in CEM-GFP T cells." (PMID 28184007, 2017). "The interaction was further confirmed similarly under endogenous conditions by means of co-IP and reverse co-IP using cyclin F and Vif antibodies in HIV-1-infected (0.5 m.o.i.)CEM-GFP cells harvested 72 h post-infection." (PMID 28184007, 2017). "Further expression analysis of cyclin F at mRNA and protein levels in infected CD4+ T cells confirmed its significant down-regulation with infection." (PMID 28184007, 2017). "However, we did not observe any change in cyclin F expression with increasing doses of Vif, thus indicating that Vif may not be directly responsible for the cyclin F down-regulation observed during infection." (PMID 28184007, 2017).
CCNF also shares sentences with these, for which no sentence is quoted: adrenocortical carcinoma (3 papers); Burkitt lymphoma (2); cervical cancer (2); cervical squamous cell carcinoma (2); clear cell renal cell carcinoma (2); diffuse large B-cell lymphoma (2); endocervical adenocarcinoma (2); endometrial cancer (2); lymphoid neoplasm (2); mesothelioma (2); sarcoma (2); stomach cancer (2); thyroid carcinoma (2); allergic asthma (1); bladder carcinoma (1); brain astrocytoma (1); brain glioma (1); breast adenocarcinoma (1); breast tumor (1); colon adenocarcinoma (1); colon adenoma (1); Dysarthria (1); esophageal carcinoma (1); germ cell tumor (1); liposarcoma (1); lymphoma (1); malaria (1); medulloblastoma (1); motor neuron disease (1); mucinous adenocarcinoma of the (1).
A further 10 diseases each share a sentence with CCNF in 1 paper.